FGFR3 (fibroblast growth factor receptor 3)
Diseases named in the same sentence as FGFR3 in open-access papers (continued):
Sharing a sentence is not in itself a finding about the gene and the disease.
carcinoma in situ (16 papers, 2012 to 2025). "In addition to FGFR3 overexpression, FGFR3 mutations more frequently found in carcinoma in situ are believed to contribute to the development of superficial bladder cancer." (PMID 36675289, 2023). "Another study has been shown that the prevalence of FGFR3 mutation was significantly higher in pTa tumors compared with carcinoma in situ (CIS), pT1, and pT2–4 among a sub population of BCa patients." (PMID 32795296, 2020). "Accordingly, FGFR3 activating mutations were associated with early, non invasive, low grade papillary tumors and never found in carcinomas in situ." (PMID 23902722, 2013). "We also found that FGFR3 alterations were linked with the absence of LVI and carcinoma in situ, supporting their known effect as biomarkers associated with better outcomes." (PMID 39335667, 2024). "FGFR3 mutation was commonly linked with the absence of LVI and carcinoma in situ and TERTp mutation with larger tumor size (p = 0.048)." (PMID 39335667, 2024).
thanatophoric dysplasia type 1 (16 papers, 2012 to 2026). Thanatophoric dysplasia type 1 (TD1) is a form of TD characterized by short, bowed femurs, micromelia, narrow thorax, and brachydactyly. "Dermal fibroblasts from patients with thanatophoric dysplasia type I (TD1) with heterozygous mutations in FGFR3 were harvested." (PMID 34831254, 2021).
Crouzon syndrome (15 papers, 2012 to 2025). Crouzon disease is characterized by craniosynostosis and facial hypoplasia. "This rare disease is caused by missense mutations in the FGFR3 gene (4p16.3; MIM 134934) encoding fibroblast growth factor receptor 3 as opposed to the differently located FGFR2 gene (10q26.13; MIM 176943) which is linked to the classic phenotype of Crouzon syndrome (CFD1; 10q26.13; MIM 123500)." (PMID 32916978, 2020).
hepatocellular carcinoma (15 papers, 2018 to 2024). A malignant tumor that arises from hepatocytes. "However, the role of PTEN and FGFR3 gene mutations in the EMT process in hepatocellular carcinoma still needs further analysis." (PMID 34178679, 2021). "FACS, MTT assay and/or growth curves served to identify the FGFR3‐IIIb/IIIc ligand being most effective to induce growth of hepatoma/hepatocarcinoma cell lines, established from human HCC." (PMID 32378800, 2020). "This was first and indirect evidence that in the hepatoma/hepatocarcinoma cells FGF9 acts largely via FGFR3‐IIIb/IIIc." (PMID 32378800, 2020). "Overexpression of fibroblast growth factor receptor 3 (FGFR3) correlates with more severe clinical features of hepatocellular carcinoma (HCC)." (PMID 33097695, 2020). "Recently, overexpression of the fibroblast growth factor receptor 3 (FGFR3) splice variants FGFR3‐IIIb and FGFR3‐IIIc was found in ~50% of hepatocellular carcinoma (HCC)." (PMID 32378800, 2020). "This was strong evidence that FGF9 is a driver of the aggressive phenotype of hepatoma/hepatocarcinoma cells, mediated via FGFR3‐IIIb and/or FGFR3‐IIIc." (PMID 32378800, 2020). "As a crucial regulator of cell growth and survival, Fgfr3 is frequently up-regulated in various cancers including hepatocellular carcinoma." (PMID 30462643, 2018). "A pre-clinical study suggested that βKlotho mediates FGF9 pro-survival functions in hepatocellular carcinoma via FGFR3 and FGFR4 and may be useful in selecting patients who could benefit from anti-FGFR therapies." (PMID 37958253, 2023). "To conclude, these data together provide evidence that the FGF9 effects on hepatoma/hepatocarcinoma cells may be mediated mainly by FGFR3‐IIIb/IIIc." (PMID 32378800, 2020). "Nevertheless, FGF9 elicited proliferation of hepatoma/hepatocarcinoma cells independent of their FGFR3‐splice variant profile, which could be blocked by knockdown of FGFR3 and not of the other FGFRs." (PMID 32378800, 2020). "Among all FGFR3‐IIIb/IIIc ligands tested, FGF9 was the most potent growth factor for hepatoma/hepatocarcinoma cells." (PMID 32378800, 2020). "In hepatoma/hepatocarcinoma cells FGF9 enhanced the capability for clonogenicity and disintegration of the blood and lymphatic endothelium, being most pronounced in cells overexpressing FGFR3‐IIIb or FGFR3‐IIIc, respectively." (PMID 32378800, 2020). "In response to FGF9, FGFR3‐IIIb overexpressing hepatoma/hepatocarcinoma cell lines formed even larger clones than the vector controls, while FGF9‐treated cells with overexpressed FGFR3‐IIIc showed an elevated migratory phenotype, as indicated by the wound‐healing and transwell assay." (PMID 32378800, 2020). "When compared to other FGFR3‐IIIb/IIIc ligands, FGF9 is the most efficient growth factor under our conditions and may act not only on human hepatoma/hepatocarcinoma cell lines but also on unaltered hepatocytes as well as on early stages of hepatocarcinogenesis." (PMID 32378800, 2020). "This is in line for instance with hepatocellular carcinoma (HCC) where recent data suggest high expression of FGFR2 and FGFR3 as potential biomarkers for infigratinib response." (PMID 31527449, 2019). "Moreover, upregulation of cancer-specific isoforms of TP73, CDH17, KLF6, FGFr2, FGFR3, DNMT3b3, and OPN has been reported in human hepatocellular carcinoma (HCC) and promoted cell cycle progression, proliferation, invasion and metastasis." (PMID 35463320, 2022).
hepatocellular carcinoma (continued). "STAT1 was significantly positively correlated with PD1 (r = 0.448), PD-L1 (r = 0.444), CTLA-4 (r = 0.436), FGFR2 (r = 0.354), FGFR3 (r = 0.36), and IDO1 (r = 0.387) in HCC, suggesting that targeting STAT1 may improve the efficacy of immunotherapy for hepatocellular carcinoma." (PMID 35646925, 2022).
ovarian carcinoma (15 papers, 2014 to 2025). A malignant neoplasm originating from the surface ovarian epithelium. "The association between the FGFR3 gene mutation and ovarian cancer has been the primary focus of research." (PMID 38534733, 2024). "For instance, SC4 has a unique pathway called “Signaling by FGFR3 point mutants in cancer” that has been previously associated with urothelial, breast, endometrial, squamous lung cancers, and ovarian cancer." (PMID 35439935, 2022). "FGFR3 overexpression enhances the cisplatin resistance in ovarian cancer through elevating the phosphorylation of the epidermal growth factor receptor (EGFR) and further activating the PI3K/AKT signaling pathway." (PMID 38542707, 2024). "Fibroblast growth factor receptor 3 (FGFR3) is expressed at high levels in cisplatin-resistant ovarian cancer cells." (PMID 38542707, 2024). "FGFR2 and FGFR3 are highly expressed in ovarian cancer tissues and their expression level is correlated with the poor survival outcome of patients with ovarian cancer." (PMID 34639155, 2021). "We observed the upregulation of FGFR2 and FGFR3 expression in patients with ovarian cancer." (PMID 34639155, 2021). "Moreover, in fact, the negative regulation of FGFR3 by mir-100 has been demonstrated in clear cell ovarian cancer cells." (PMID 28320388, 2017). "In ovarian cancers, OPCML drives inactivation and degradation of the RTKs HER2, HER4, FGFR1, FGFR3, EPHA2, and AXL, and the specificity of this network is underscored by identification of a group of RTKs that are unaffected by OPCML." (PMID 40699804, 2025).
endometrial cancer (14 papers, 2014 to 2025). Primary or metastatic malignant neoplasm involving the endometrium (mucous membrane that lines the endometrial cavity). "Regarding FGFR3 mutation in relation to therapeutic response, a previous study illustrated that the FGFR3-targeting drug anlotinib has better treatment efficacy in endometrial cancer than conventional chemotherapy with carboplatin and paclitaxel." (PMID 33143664, 2020). "FGFR1 and FGFR3 amplifications are also found in endometrial cancer through integrating genomic characterization of somatic copy number alterations." (PMID 33193890, 2020). "Somatic mutations in FGFR1, FGFR2, FGFR3, and FGFR4 genes are reported in endometrial cancer." (PMID 33193890, 2020).
non-small cell lung carcinoma (13 papers, 2015 to 2026). A group of at least three distinct histological types of lung cancer, including non-small cell squamous cell carcinoma, adenocarcinoma, and large cell carcinoma. "Further, FGFR3 (K650E), a product of an activating mutation, was identified in glioma, non-small-cell lung carcinoma (NSCLC), ES, and liposarcoma (LPS), and correlated with poor survival in patients with LPS." (PMID 32754598, 2020). "Amplification of FGFR1 occurs for instance, in non small cell lung cancer (NSCLC) and breast cancer, while mutations of FGFR3 are found in bladder and cervix carcinoma." (PMID 29152117, 2017).
Camptodactyly (12 papers, 2015 to 2024). The distal interphalangeal joint and/or the proximal interphalangeal joint of the fingers or toes cannot be extended to 180 degrees by either active or passive extension. "FGFR3 has been reported to cause CATSHL syndrome (camptodactyly, tall stature, scoliosis, and hearing loss), and we identified two novel variants, c.1286C>T (p.A429V) and c.1450G>A (p.G484S), which formed a compound heterozygous genotype in one case." (PMID 39336818, 2024). "The variant had been described with controversial status, but FGFR3 was already associated with camptodactyly, tall stature, and hearing loss syndrome (CATSHLS)." (PMID 39498320, 2024). "CATSHL (camptodactyly, tall stature, and HL) syndrome is caused by loss-of-function mutations in the fibroblast growth factor receptors 3 (FGFR3) gene." (PMID 37210555, 2023). "CATSHL syndrome, characterized by camptodactyly, tall stature and hearing loss, is caused by loss-of-function mutations of fibroblast growth factor receptors 3 (FGFR3) gene." (PMID 32641982, 2020). "Heterozygous los-of-function mutations of fibroblast growth factor receptor-3 (FGFR3) gene results in a aphenotype characterized by camptodactyly, tall stature and hearing loss (CATSHL syndrome." (PMID 28774346, 2017). "The phenotype of FGFR3−/− mice overlaps with that of individuals carrying a missense mutation in the tyrosine kinase domain of FGFR3 that results in camptodactyly, tall stature, and hearing loss or CATSHL syndrome (OMIM 610474)." (PMID 25852647, 2015). "However, the presence of camptodactyly associated with hearing loss and a likely pathogenic variant in FGFR3 pointed to a phenotype related to the CATSHL syndrome spectrum." (PMID 39498320, 2024). "Ablation of Fgfr3 in mice causes the expansion of proliferating and hypertrophic chondrocytes, whereas in humans, loss-of-function pathogenic variants in the FGFR3 gene could cause the camptodactyly, tall stature, scoliosis, and hearing loss (CATSHL) syndrome." (PMID 36232472, 2022). "As the deletion of the hs2696 enhancer resulted in a dramatic decrease of Fgfr3 transcript, variants affecting enhancers could induce Camptodactyly, Tall Stature, and Hearing Loss (CATSHL) syndrome as known for the Fgfr3 loss-of-function in humans." (PMID 38844479, 2024). "In contrast, a loss-of-function mutation in Fgfr3 in humans causes camptodactyly, tall stature, and hearing loss (CATSHL) syndrome (OMIM 610474), and Fgfr3 deletion in mice leads to skeletal overgrowth due to enhanced proliferation of growth plate chondrocytes." (PMID 26091072, 2015).
pancreatic cancer (12 papers, 2013 to 2025). "Of note, according to the cancer genome atlas database, FGFR3 is barely expressed in the pancreas or in pancreatic cancer which has also been proven by qPCR." (PMID 32457900, 2020). "Furthermore in pancreatic cancer, where FGFR3 expression is downregulated, FGFR3 functions as a tumor suppressor in cancer cells of epithelial phenotype and an oncogene in cells of mesenchymal phenotype, highlighting context-dependent functional roles." (PMID 31987043, 2020). "We explored the actions of FGFR3 in modulating pancreatic cancer cell behavior." (PMID 23902722, 2013). "Thus, FGFR3 transcripts and protein seemed to be lost in a non negligible proportion of pancreatic tumors, especially in endocrine tumors." (PMID 23902722, 2013). "In human pancreatic carcinoma tissues, levels of FGFR3 dropped in tumors." (PMID 23902722, 2013). "FGFR3 and ARID1A mutations may represent actionable targets in TACSTD2-high urothelial cancer, while KRAS mutations may be an attractive target for TACSTD2-high CRC and pancreatic cancer." (PMID 38986529, 2024). "Moreover, little is known on FGFR3 actions in pancreatic tumors." (PMID 23902722, 2013).
lung squamous cell carcinoma (11 papers, 2014 to 2023). "Liao and colleagues reported in 2013 the identification of inhibitor-sensitive oncogenic FGFR2 and FGFR3 mutations in lung squamous cell carcinoma from the Cancer Genome Atlas (TCGA) dataset." (PMID 26486077, 2015). "Six (1.2%) FGFR3 activating mutations were identified in lung squamous cell carcinoma (five S249C and one R248C)." (PMID 26486077, 2015). "All the 6 lung squamous cell carcinoma patients with oncogenic FGFR3 mutations were male, and 5 of them were ever smokers." (PMID 26486077, 2015). "However, we screened more than 500 Chinese lung squamous cell carcinoma samples, and found that oncogenic FGFR3 mutations were present in only 1.2% (5 S249C and 1 R248C)." (PMID 26486077, 2015). "The squamous cell lung carcinomas showed two cases with ARID1A loss of function variants (E1718* and G1848fs), one FGFR3 S249C variant, one MAP2K1 P124L, and one case with PIK3CA amplification and E545A variant." (PMID 36125633, 2023). "We sequenced 503 lung squamous cell carcinoma resected from October 2007 to March 2013 for the prevalence of activating FGFR2 and FGFR3 mutations." (PMID 26486077, 2015). "Herein, we present the novel finding that increased FGFR3 mRNA expression might be a negative prognostic marker in terms of the risk of recurrence of squamous cell lung cancer." (PMID 36142417, 2022).
osteogenesis imperfecta (11 papers, 2021 to 2026). Osteogenesis imperfecta (OI) comprises a heterogeneous group of genetic disorders characterized by increased bone fragility, low bone mass, and susceptibility to bone fractures with variable severity. "The most common nosology groups in this study were the FGFR3 chondrodysplasia group, the achondrogenesis and osteogenesis imperfecta and decreased bone density group, which was consistent with those previously reported." (PMID 41457519, 2026).
urothelial cell carcinoma (11 papers, 2014 to 2021). "FGFR3 mutations are frequent in superficial urothelial cell carcinoma (UCC) as oncogenic activation of FGFR3 is predicted to result in stimulation of the MAPK pathway." (PMID 34229750, 2021). "Fibroblast growth factor receptor 3 (FGFR3) alternations are associated with urothelial cell carcinoma pathogenesis." (PMID 32397531, 2020). "In another phase I trial BGJ398 also showed evidence of clinical activity in patients with solid tumors harboring FGFR aberrations, including 4 of 5 patients with urothelial cell carcinomas (4 of which originated in the bladder) with FGFR3-activating mutations." (PMID 27409839, 2016).
developmental delay (10 papers, 2012 to 2025). "Moreover, in humans, a potentially inactivating mutation in the catalytic domain of human FGFR3 causes developmental delay and, in some patients, microcephaly." (PMID 39115595, 2024). "In addition, the observation of a global developmental delay could not be definitively separated from the consequences of the identified FGFR3 mutation." (PMID 27370225, 2016). "These outcomes indicated the potential relationship between FGFR3, ALOX5, and developmental delay." (PMID 36358993, 2022). "Combining the Gene ontology analysis results and Human Brain Transcriptome database, we showed that FGFR3 and ALOX5 could serve as novel developmental delay candidate genes." (PMID 36358993, 2022).